AHR (aryl hydrocarbon receptor)
Diseases named in the same sentence as AHR in open-access papers (continued):
Sharing a sentence is not in itself a finding about the gene and the disease.
allergic disease (continued). "Thus, studies on the cross-regulation between AhR and TGFβ1 signaling might be essential for better understanding of the underlying mechanisms for the synergic effects between environmental chemicals and allergens on the development of allergic diseases." (PMID 24795504, 2014). "Recent evidence supports a significant link between environmental exposure and AhR in the development of allergic diseases." (PMID 24795504, 2014). "Indole-3-lactic acid (I3LA) is a metabolite of Trp, and indole derivatives participate in the differentiation of immune cells and the synthesis of cytokines via the aryl hydrocarbon receptors (AhR) to regulate the immune responses and participate in anti-inflammatory and allergic reactions." (PMID 36362303, 2022). "This review discussed how AhR mediates immune responses in allergic diseases." (PMID 36601108, 2022). "It has been well established that AhR plays a modulatory role in mediating the innate and adaptive immune response to combat various infectious diseases, metabolic diseases, cancer, and allergic diseases." (PMID 36601108, 2022). "In the group of patients with high AhR expression, patients with skin lesions, allergies, and lower levels of the C3 fraction in the complement were more frequent than in the group with low expression of AhR, indicating AhR as a potential biomarker for predicting skin lesions in SLE." (PMID 36136068, 2022). "Similarly, metformin, which acts as an anti-diabetic drug, can also influence the activity of AhR in mast cells to treat allergic diseases." (PMID 36601108, 2022). "Altogether, these data suggest that AhR in mast cells may play a role in the immediate allergic reaction." (PMID 33233810, 2020). "The findings may suggest a possible biological link between environmental exposure and AhR in modulating allergen-induced allergic diseases." (PMID 24795504, 2014). "Recent discoveries regarding AhR and environmental toxicant interaction and its influence on immune responses highlight the potential link between environmental exposure and AhR in modulating allergen-induced allergic diseases." (PMID 24795504, 2014). "Given the importance of the AhR for the induction of regulatory immune cell subsets and the principle of AIT, which is based on tolerance induction towards the allergy-eliciting allergens, it was somewhat unexpected that AhR deficiency did not change the therapeutic outcome of AIT in this study." (PMID 38915403, 2024). "Additionally, EC might have the potential to prevent or treat allergic diseases that involve IgE and mast cells since intrinsic AhR activity may play an important role in shaping allergic inflammation." (PMID 37373144, 2023). "This study also showed that IgE-mediated mast cell activation might occur in the context of background endogenous AhR activity in vivo, suggesting that the blockade of the AhR signaling by EC might be beneficial for allergic diseases involving IgE and mast cells." (PMID 37373144, 2023). "Taken together, we suggest that AhR plays a role in modulating cockroach allergen-induced immune responses by controlling the active TGFβ1 release, and there is a possible synergistic effect between exposure to allergens and environmental chemicals on the development of allergic diseases." (PMID 24795504, 2014). "Thus, dietary ligands of the AhR may have anti-inflammatory, anti-allergy, anti-cancer, and immunoregulatory effects." (PMID 24747651, 2014). "In line with the immunosuppressive effects of TCDD via Tregs stimulation following AhR ligation/activation, TCDD has also demonstrated suppressive (preventive) effects in rodent allergy models." (PMID 25883945, 2015). "Bifidobacterium-derived ILA, which was higher in the non-AAM fecal water, has anti-inflammatory and allergy protective effects on the immature immune system through AhR and TLR-4." (PMID 40954473, 2025). "AhR regulates allergic diseases in both canonical and non-canonical pathways." (PMID 36601108, 2022).
allergic disease (continued). "Thus, there seems to be no (protective) effect of I3C regarding allergy induction and B cell activity, which is in line with results regarding peanut allergy in AhR-KO mice." (PMID 28666018, 2017). "Interestingly, other AhR ligands did not have this suppressive effect on the allergy development, suggesting that the effect via AhR is ligand specific." (PMID 25883945, 2015).
breast tumors (23 papers, 2011 to 2025). "In ER+ tumours, 39 genes were upregulated, while two genes were downregulated, in AHR-high vs. AHR-low breast tumours." (PMID 40646277, 2025). "The analysis revealed that AhR protein levels are slightly increased in the primary breast tumor cohort as compared to normal tissue." (PMID 38459088, 2024). "To investigate the clinical relevance of AhR and GPR30, we performed RT-qPCR analyses to explore GPR30 and AhR mRNA expression levels in a cohort of 113 human primary breast tumor samples." (PMID 32670863, 2020). "IGF1R and TGFB1 were significantly overexpressed in the highest AHR-expressing group, but only in ERα-positive breast tumors (p = 0.0088 and p = 0.0035, respectively)." (PMID 29320557, 2018). "AHRR mRNA level was significantly twofold higher in high AHR-expressing breast tumors compared to low AHR-expressing tumors, but only in the ERα-negative subpopulation (p = 0.0036)." (PMID 29320557, 2018). "IDO1 mRNA levels were significantly increased in high AHR-expressing breast tumors relative to low AHR-expressing breast tumors in both ERα subpopulations." (PMID 29320557, 2018). "Statistical analysis of mRNA expression of AHR signaling pathway genes relative to AHR mRNA expression and ERα status in two breast tumor subpopulations." (PMID 29320557, 2018). "We further extended our studies of BRCA-1/AhR cross-talk to human breast tumors, and found that compared to LUM-A, LUM-B, and HER-2-positive tumors, TNBC had higher AhR and BRCA-1 CpG methylation." (PMID 26715507, 2015). "Next, we wished to explore if differential expression of AhR and BRCA-1 promoter CpG methylation associated with pathological classification of human breast tumor subtypes based on receptor status." (PMID 26715507, 2015). "Previous results from our research group have demonstrated that the antitumor effect of compounds of the 2-(4-amino-3-methylphenyl) benzothiazole group (DF 203, NSC 674495; 5F 203, NSC 703786) is mediated by AhR in MCF-7 breast tumor cells." (PMID 22295239, 2011). "Hence, AhR activation in breast tumour tissue promotes a chronic inflammatory state, especially in more aggressive subtypes, including triple-negative breast cancer (TNBC)." (PMID 40646277, 2025). "Indeed, AHR overexpression that is correlated with elevated expression of inflammatory markers, including interleukin-8 (IL-8), has been observed in human breast tumors." (PMID 38982523, 2024). "In fact, a recent study in a cohort of 439 breast tumors showed that high AHR expression correlated with the up-regulation of genes involved in inflammation, metabolism, invasion and growth factor signaling while high AHRR mRNA levels correlated with good-metastasis free survival." (PMID 32286485, 2020). "Although a complete view of the role of AHR in breast tumor growth is not currently available, AHR activation has been extensively linked with malignant transformation." (PMID 32286485, 2020). "100% of tumor samples were positively stained for cytoplasmic AhR in breast tumor cells." (PMID 29320557, 2018). "IL1B, IL6, TNF, IL8 and CXCR4 mRNA levels were significantly increased in the high AHR-expressing ERα-negative breast tumor subpopulation, while these associations were only observed for IL6 and CSF1 in the ERα-positive tumor subgroup." (PMID 29320557, 2018). "However, in their study, AhR status was based on a 10% immunocytochemical positivity threshold of carcinoma cells in breast tumors (n = 90), while the present study analyzed both on AhR protein and mRNA." (PMID 29320557, 2018). "However, in esophageal, pancreatic, and breast tumors, AHR is localized in the cytoplasm and the AHR-expressing status is inversely correlated with the histological grade of patients." (PMID 27752740, 2017).
breast tumors (continued). "Since CXCR4 has both functional and prognostic significance for metastasis in breast tumors and cells, the antimetastatic activity of omeprazole and other AHR-active pharmaceuticals including other benzimidazole protein pump inhibitors are currently being investigated." (PMID 25011475, 2014). "However, relatively little is known about the role of AhR in human primary breast tumors." (PMID 29320557, 2018). "Finally, BRCA1 mRNA expression was strongly associated with high AHR-expressing breast tumors in the ERα-negative subpopulation (p = 0.0000023)." (PMID 29320557, 2018). "We conclude that constitutive high expression of AhR associated with BRCA-1 gene hypermethylation may be prognostic markers of ERα-negative breast tumor development." (PMID 26715507, 2015). "Increased expression and activation of the AhR may contribute to epigenetic remodeling during early breast carcinogenesis, whereas loss of BRCA-1 associates with ERα-negativity in hereditary and sporadic breast tumors." (PMID 26715507, 2015). "Finally, we examined the association between expression of AhR and BRCA-1 promoter CpG methylation in human triple-negative (TNBC), luminal-A (LUM-A), LUM-B, and epidermal growth factor receptor-2 (HER-2)-positive breast tumor samples." (PMID 26715507, 2015). "Interestingly, murine breast tumors induced with DMBA generally express extremely high AHR levels." (PMID 22952704, 2012). "A strong correlation was therefore demonstrated between AHR, IDO1 and TDO2 expression in breast tumors." (PMID 29320557, 2018). "TNBC exhibited increased basal AhR and BRCA-1 promoter CpG methylation compared to LUM-A, LUM-B, and HER-2-positive breast tumors." (PMID 26715507, 2015). "Certain agents, including the AhR agonist aminoflavone (AFP464) and the AhR antagonist StemRegenin-1 (SR1), have been tested in clinical trials for breast neoplasms and solid tumors (NCT01015521, NCT00369200, NCT01233947) or hematological malignancies (NCT02765997), respectively." (PMID 38807762, 2024). "TDO2 mRNA levels were also significantly increased in high AHR-expressing breast tumors, but only in the ERα-negative subpopulation." (PMID 29320557, 2018). "A complete overview of the role of AhR in breast tumor growth is not currently available, especially as most studies have been conducted on cell culture and rodent models." (PMID 29320557, 2018). "The aim of this study was to identify the type of breast tumors (ERα-positive or ERα-negative) that express AHR and how AhR affects human tumorigenesis." (PMID 29320557, 2018). "AHR mRNA expression was significantly different between the low AHR-expressing and high AHR-expressing breast tumor groups in both the ERα-negative (p<0.0000001) and ERα-positive (p = 0.0000067) subpopulations." (PMID 29320557, 2018). "In line with the objective of this study, immunohistochemistry was performed on paraffin sections to assess the localization of AhR protein on a total of 30 ERα-positive or ERα-negative breast tumors." (PMID 29320557, 2018). "Higher AHR mRNA expression levels therefore appear to be strongly involved in inflammation processes, mainly in ERα-negative breast tumors." (PMID 29320557, 2018). "The potential prognostic significance of the current findings is underscored by the fact the AhR is constitutively active in ERα-negative human breast tumor cells." (PMID 26715507, 2015). "Finally, we document that human TNBC had higher AhR expression and BRCA-1 promoter CpG methylation compared to human luminal-A (LUM-A), LUM-B, and HER-2-positive breast tumors." (PMID 26715507, 2015). "They assessed the expression of AHR both in ERα-positive or ERα-negative human breast tumors and found in ER-positive cells a correlation between AHR expression, metastasis occurrence and related markers (MMP1, MMP2), and plasminogen activator urokinase (PLAU)." (PMID 32722276, 2020).
breast tumors (continued). "Interestingly, IDO1 levels, but not IDO2 levels (not expressed), were significantly elevated in high AHR-expressing breast tumors compared to low AHR-expressing breast tumors in both ERα subpopulations." (PMID 29320557, 2018). "Recent studies indicate that AhR could also play distinct roles in the survival, migration and invasion of ERα-positive as compared to ERα-negative breast tumor cell lines in the absence of environmental chemicals." (PMID 29320557, 2018). "In a series of 439 ERα-positive or ERα-negative breast tumors, representing the different molecular subtypes, large ranges of AHR (0–5.8-fold difference) and AHRR (0–19.8-fold difference) mRNA expression were observed, reflecting extensive heterogeneity of gene expression in tumor samples." (PMID 29320557, 2018). "Constitutive AhR expression coupled to BRCA-1 promoter CpG hypermethylation may be predictive markers of ERα-negative breast tumor development." (PMID 26715507, 2015). "Therefore, AhR-dependent repression of BRCA-1 via increased CpG methylation may disrupt this positive feedback loop between BRCA-1 and ERα and favor the development of ERα- and BRCA-1-negative breast tumors." (PMID 26715507, 2015). "Two well-known ligands for AHR (TCDD and BaP) induced mRNA expression of IL1B and IL6 in an ERα-negative breast tumor cell line." (PMID 29320557, 2018). "Nevertheless, the connection between higher AhR expression and/or activation and BRCA-1 promoter hypermethylation in breast tumors has not been investigated." (PMID 26715507, 2015). "The strong correlation between high AHR and ARNT levels in both ERα-negative and ERα-positive tumors also suggests that the heterodimer, AHR-ARNT (AHR nuclear translocator), could be active in breast tumors." (PMID 29320557, 2018).
systemic lupus erythematosus (23 papers, 2015 to 2026). An autoimmune multi-organ disease typically associated with vasculopathy and autoantibody production. "Specifically, AhR signaling in macrophages has been reported to promote anti-inflammatory M2 phenotype with increased IL-10 production in mouse models of lupus, associated with reduced production of anti-dsDNA autoantibodies." (PMID 30944419, 2019). "Exposure of phagocytes to apoptotic cell-associated DNA (a common antigenic source in experimental lupus), upregulated the expression of the transcription factor AhR (aryl hydrocarbon receptor) in a TLR9-dependent manner." (PMID 31354738, 2019). "AhR activation could upregulate genes encoding cytokines such as IL-10 that regulate immune tolerance in lupus." (PMID 34335588, 2021). "Therefore, loss of TLR9 or AhR in lupus prone mice exacerbated disease." (PMID 31354738, 2019). "hUC-MSC transplantation increased AHR and ZO-1 expression in colon epithelial cells of lupus mice, while FMT inhibited this regulation." (PMID 40251524, 2025). "The pharmacological manipulation of AhR activity has also been identified as an effective intervention for delaying the progression of spontaneous lupus‐like symptoms in mouse models." (PMID 37382269, 2023). "We aimed to investigate the therapeutic effect of the AhR agonist tapinarof during the development of systemic lupus erythematosus (SLE)." (PMID 37382269, 2023). "In systemic lupus erythematosus, the expression of AhR is increased on the surface of macrophages susceptible to apoptotic cells, which eventually promotes the secretion of immunosuppressive cytokine IL-10; thus, limits the pathogenesis of SLE in-vivo." (PMID 36601108, 2022). "Later studies in lupus CD4+ T cells demonstrated that ultraviolet B strongly activates AhR, which subsequently contributes to the low expression of SIRT1 by binding to the SIRT1 promoter." (PMID 33981300, 2021). "AhR–ROR-γt complex is a therapeutic target for MAP4K3/GLKhighIL-17Ahigh subpopulation of systemic lupus erythematosus." (PMID 31318609, 2019). "AhR agonists have also been shown to directly induce IL-10 responses in myeloid cells to counter autoimmune disorders such as lupus." (PMID 30944419, 2019). "The activation of aryl hydrocarbon receptor (Ahr), a cellular environmental sensor, might aggravate activity of the lupus-like condition." (PMID 33919603, 2021). "Interestingly, aged female C57BL/6 mice with a myeloid lineage AhR deletion develop a systemic lupus erythematosus (SLE)-like phenotype with chronic immune system activation and kidney pathology relative to WT mice." (PMID 32260098, 2020). "It will be interesting to assess whether indigo as an AhR agonist has a capacity to alter immunity against nucleic acid targeting pathways in IR or whether it also has effects on lupus." (PMID 30944419, 2019). "Furthermore, UV exposure elicits AHR activation and the generation of FICZ, which is a high-affinity ligand for AHR activation and can further promote the differentiation of the Th17 cell population, thereby worsening the severity of lupus." (PMID 27597882, 2016). "Thus, AHR-FICZ signaling is an integral part of the UVB stress response, and the AHR may, therefore, represent a target for therapeutic intervention in lupus." (PMID 27597882, 2016). "In CD4+ T cells from lupus patients, low activity of DNMT1 has been observed after activation of AhR by UVB." (PMID 32899152, 2020). "Consequently, AhR knockout induced autoimmune responses and systemic lupus erythematosus (SLE) disease in a mouse model." (PMID 31214024, 2019). "Studies on lupus CD4+ T cells have shown that UV-B radiation inhibits SIRT1-mRNA and protein expression by activating AhR and suppressing DNMT1 activity in CD4+ T cells by binding upstream of the SIRT1 promoter translation initiation site, thus mitigating the progression of the pathological process." (PMID 37483618, 2023).
systemic lupus erythematosus (continued). "Additionally, the reduced expression of AHR and ZO-1 in the MSC-FMT group underscores the role of the gut microbiome in lupus-prone mice, suggesting that alterations in the gut microbiota can decrease the expression of these proteins, leading to intestinal injury." (PMID 40251524, 2025).